TNF (tumor necrosis factor)
Diseases named in the same sentence as TNF in open-access papers (continued):
Sharing a sentence is not in itself a finding about the gene and the disease.
tumor (continued). "The critical breakthrough occurs when inflammatory cytokines (TNF-α, IL-1β) increase tumor cell MHC-I expression and enhance antigen processing machinery, making previously cryptic tumor epitopes available for cross-presentation." (PMID 41012173, 2025). "For patients with tumors, tumor cells release a variety of cytokines such as interleukin‐1 (IL‐1), IL‐6, and TNF‐α, which can stimulate osteoclast differentiation via multiple mechanisms and disrupt the balance of bone remodeling." (PMID 40989575, 2025). "Using orthotopic Panc02 model, DKO of TNF-α/IL-1 receptors consistently rescued the tumor growth suppression phenotype induced by Cad KO." (PMID 41243973, 2025). "TNF-α enhances tumor cell invasiveness through the NF-κB pathway and promotes epithelial-mesenchymal transition (EMT), granting cancer cells migratory and metastatic potential, which are critical in CRC progression and metastasis." (PMID 40995229, 2025). "Random forest analysis identified tumor stiffness, IL-10, and TNF-α as the strongest predictors of therapeutic outcome." (PMID 41391724, 2025). "By producing pro-inflammatory cytokines like TNF-α and IL-1β, neutrophils can enhance tumor cell proliferation and survival, thereby indirectly supporting tumor growth." (PMID 40486614, 2025). "Cytokines like IL-6 and TNF-α, as well as tumor-infiltrating lymphocytes (TILs), also serve as key indicators of immune activation." (PMID 40092992, 2025). "Functional assays demonstrated that the NF-κ B activator TNF-α effectively counteracted the inhibitory effects of NMB silencing on tumor cell proliferation, migration, and invasion." (PMID 40486508, 2025). "NO reacts with ROS to generate ONOO−, which impairs ROS-mediated NF-κB activation, thereby restoring tumor cell sensitivity to TNF-α-induced apoptosis." (PMID 41036604, 2025). "Reciprocally, PRDX1 ablation in macrophages restrains M2 polarization and enhances T‐cell‐mediated anti‐tumor immunity by promoting the secretion of inflammatory factors (IL‐1β and TNFα) via activation of JAK‐STAT1/NF‐κB signaling pathways." (PMID 41306557, 2025). "Th1 cells have dual roles, secreting TNF‐α, which, when chronically low, can promote tumor growth, while prolonged exposure can induce immunosuppression." (PMID 39817507, 2025). "NF-κB1 p50 is particularly critical in sustaining the M2 phenotype; its inhibition reprograms TAMs toward an M1-like state, characterized by the production of TNF-α, IL-12, and iNOS, enhancing tumor cell killing." (PMID 40562870, 2025). "Regarding chemoresistance, the production of TNF-α and IL-6 contributes to a tumor-promoting microenvironment." (PMID 40404908, 2025). "CTLs also produce cytokines such as IFN-γ and TNF-α, further enhancing the anti-tumor immune response." (PMID 39911388, 2025). "TNF-α, while initially identified for its ability to induce tumor cell death, has a more complex role in cancer biology." (PMID 40563999, 2025). "SLC7A11 and SLC3A2 expression in tumor cells wasalso suppressed by TNF-α: decreased cystine uptake led to cell death dueto oxidative stress development." (PMID 40264585, 2025). "In AOM/DSS-induced CRC mice, KGM-CUR/PSM microspheres significantly improved survival and inhibited CRC tumor growth, and effectively reduced the expression of inflammatory cytokines (TNF-α, IL-1β, IL-6) and myeloperoxidase (MPO)." (PMID 40733148, 2025). "F. nucleatum can also induce the release of pro-inflammatory cytokines such as IL-6 and TNF-α, creating an inflammatory microenvironment that promotes tumor development." (PMID 40313460, 2025). "HMGB2 silencing or knockout enhanced NK cell cytotoxicity, evidenced by increased granzyme B, perforin, IFN-γ, and TNF-α, and higher tumor cell lysis." (PMID 41280896, 2025). "In contrast, γδ TILs not only significantly increased CD107a expression when exposed to tumor digest (P = 0.008), but also substantially increased the production of TNF and IFNγ (TNF: P = 0.03; IFNγ: P = 0.008)." (PMID 40897471, 2025).
tumor (continued). "The analysis of factors affecting microbiota-brain axis relationships through regression methods showed that CRP and IL-6 and TNF-α inflammatory markers and tumor size and disease stage and hospital stay duration had positive effects." (PMID 41451009, 2025). "The inflammatory factors produced during this process, such as IFN-β, TNF-α, IL-6, and IL-1β, play important roles in immune responses, collectively triggering systemic anti-tumor immunity and inhibiting tumor growth." (PMID 40756351, 2025). "The engineered population, designated LAMΦ-M7/8a, demonstrated the ability to phagocytose 4T1 tumor cells and secrete high levels of IL-6 and TNF-α in vitro." (PMID 41417432, 2025). "They kill tumor cells by releasing granules or inducing FasL-mediated apoptosis and release interferon-γ (IFNγ) and tumor necrosis factor α (TNFα) to induce tumor cell cytotoxicity." (PMID 40599868, 2025). "Under the distinctive pathophysiological conditions of the TME, cancer-associated inflammatory cytokines, including TNF-α, TGF-β, IFN-I, IL-1, IL-6, and IL-10, often exhibit upregulated expression, thereby modulating the biological behaviors of tumor cells." (PMID 40563367, 2025). "TAM-derived TNF-α and IL-1β activate NF-κB in tumor cells, driving inflammatory gene expression and promoting the EMT." (PMID 41584838, 2025). "Recently, GLIS (50–200 μg/mL) was also reported to activate bone marrow-derived macrophages in tumor-bearing mice, which secreted the pro-inflammatory cytokines IL-1β, TNF-α, and NO to trigger higher antitumor activities." (PMID 40733125, 2025). "First, TNF-α is able to promote angiogenesis and tumor invasion through the up-regulation of VEGF and MMPs." (PMID 41376630, 2025). "Tumor progression is regulated by various pro-inflammatory, such as interleukin (IL)-6 or TNF-α, and anti-inflammatory factors, such as IL-10 and TGF-β." (PMID 39834867, 2025). "Inflammatory cytokines, including VEGF, IL-1, IL-6, and TNF-a, are produced by tumor cells that promote cellular growth and differentiation, but concurrently cause endothelial cell dysfunction leading to greater capillary hyperpermeability." (PMID 40103850, 2025). "Secondly, TNFα affects the tumor microenvironment by regulating inflammation, angiogenesis, and cell proliferation." (PMID 40282506, 2025). "The tumor microenvironment in PC is characterized by chronic inflammation with overproduction of cytokines such as IL-6, TNF-α, and IL-1β." (PMID 41514529, 2025). "The Roselyne Tournaire group reported in 2012 and 2021 that decreased TIE1 and TNF-α signaling can induce EndMT in endothelial cells and contribute to tumor stroma formation, particularly CAF accumulation." (PMID 41154806, 2025). "ICOS, as a T cell co‐stimulatory molecule, induces the accumulation of mitochondrial reactive oxygen species (ROS) in tumor cells by promoting the secretion of pro‐inflammatory factors (such as TNF‐α), indirectly activating MPT‐related pathways." (PMID 40747615, 2025). "TNF, a critical cytokine in the tumor immune microenvironment, plays a multifaceted role in tumor initiation, progression, and anti-tumor immunity." (PMID 40520886, 2025). "Their rapid activation and production of cytokines, such as IFN-γ and TNF-α, can trigger the killing of tumor cells, either directly or indirectly." (PMID 39936958, 2025). "Subsequent studies have shown that serum TNF-α levels in BC patients are positively correlated with tumor size, TNM stage, and lymph nodes metastasis." (PMID 40251177, 2025). "In one example, intracellular ROS in medium‐high abundance of TAMs can mediate tumour aggressiveness by enhancing TNF‐alpha (TNF‐alpha) production by TAMs." (PMID 40990316, 2025). "TNF-α functions as a pro-inflammatory cytokine capable of directly inducing tumor cell apoptosis while also exerting indirect anti-tumor effects through the activation of immune cells." (PMID 41394878, 2025).
tumor (continued). "Elevated levels of pro-inflammatory cytokines such as IL6 and TNF-α, along with senescent cell accumulation, foster a tumor-permissive microenvironment." (PMID 40781676, 2025). "Tumor necrosis factor-alpha (TNF-α) is a proinflammatory cytokine produced by various host immune cells and tumor cells." (PMID 40507492, 2025). "It induces chronic inflammation via cytokines such as IL-1β, IL-6, and TNF-α, fostering tumor progression." (PMID 39941737, 2025). "Fungi induce the secretion of pro-inflammatory cytokines, including IL-17, IL-6, and TNF-α, which activate immune-suppressive mechanisms that, paradoxically, support tumor survival and progression." (PMID 40557321, 2025). "In serum, the levels of TNF-α and IL-1β were notably higher in the Tumor group in comparison to the Con group, and there was a significant downregulation in the PVSO group." (PMID 40993108, 2025). "Inflammation can inhibit T-cell function and alter the microenvironment to generate pro-tumor cytokines like IL-6 and TNF-α, thereby diminishing the anti-tumor efficacy of ICIs." (PMID 41001020, 2025). "KEGG pathway analysis highlighted the involvement of DEGs in tumor and immune microenvironment‐related pathways, such as the TNF pathway and JAK‐STAT signaling pathway." (PMID 40956367, 2025). "This phase is characterized by pro-inflammatory cytokines, including tumor TNF-α, IFN-γ, IL-1, and IL-6." (PMID 40446079, 2025). "The relative abundance of Fusobacterium nucleatum and the expression levels of cytokine genes (IL-1β, IL-6, IL-10, IL-17, TNF) were measured in tumor and adjacent normal tissues to assess their differential expression and potential associations." (PMID 41267807, 2025). "MDSC development involves tumor-driven signals and inflammatory cytokines such as IL-17A, TNF-α, and G-CSF." (PMID 40918141, 2025). "Our study positions TNF signaling as a central factor facilitating the anti-tumor efficacy of the combination treatment." (PMID 40858106, 2025). "Bacterial supplementation also increases peripheral neutrophil counts in germ-free mice, while TANs in small or early-stage tumors exhibit robust tumor-killing activity through the production of cytotoxic TNF-α and IFN-γ." (PMID 40770084, 2025). "Her work demonstrated that continuous TNFα presence creates chronic tumor inflammation that fundamentally alters tumor growth and metastasis potential." (PMID 41141601, 2025). "Pro-inflammatory cytokines, including IL-2, TNFα, IL-1β, and IL-6, contribute to shaping a tumor-promoting microenvironment by sustaining inflammation and facilitating cancer cell survival and dissemination." (PMID 41614846, 2025). "Preclinical studies demonstrate that VISTA inhibition significantly increases CD8+ T cell infiltration, enhances IFN-γ and TNF-α secretion, and restores anti-tumor immunity, particularly when combined with anti–PD-1 therapy in PD-1-resistant models." (PMID 40821795, 2025). "A reduction in levels of TNF‐α and IL‐6, cytokines known to drive tumor progression, inflammation, and metastasis formation, was observed." (PMID 40838679, 2025). "The NF-κB signaling pathway plays a key role in promoting pro-inflammatory cytokines, such as TNF-α, IL-1β, and IL-6, which are involved in tumor initiation and progression." (PMID 41154100, 2025). "During liver metastasis, metastatic tumor cells adhere to vascular endothelial cells, and TNF-α-induced endothelial E-selectin is a key factor." (PMID 41357571, 2025). "Through the activation of NF-κβ signaling, TNF-α (tumor necrosis factor-α) and IL-17 (interleukin-17) raise the expression of PD-L1 (programmed cell death protein 1) in LNCaP cells, hence promoting tumor cell motility and chemoresistance." (PMID 39891849, 2025). "Studies have also indicated that elevated TNF-α and dysregulated iron homeostasis often reinforce each other in tumor or inflammation models, collectively driving cell damage and death." (PMID 40547014, 2025).
tumor (continued). "This suppression of NF-κB activity directly translates into reduced expression of pro-inflammatory cytokines such as TNF-α, IL-6, and IL-1β, which are fundamental for tumor progression, angiogenesis, and immunosuppression." (PMID 41302515, 2025). "Pro-inflammatory cytokines such as TNF-α and IL-6, regulated by NF-κB, enhance PD-L1 expression, enabling tumor cells to interact with the programmed death-1 (PD-1) receptor on T-cells." (PMID 39949765, 2025). "Among these, the key secretory molecules, IFN-γ, CXCL10, IL-4, VEGF, and TNF-α, are mainly involved in angiogenesis and tumor progression." (PMID 41029387, 2025). "Inflammation plays a critical role in HNC progression, with elevated levels of pro-inflammatory cytokines such as TNF, IL-6, IL-8, and IL-1β contributing to tumor development." (PMID 40733296, 2025). "For instance, curcumin inhibits NF-κB and COX-2 activation, decreases secretion of IL-6 and TNF-α, and downregulates inducible nitric oxide synthase (iNOS), thereby suppressing the pro-tumor inflammatory cascade." (PMID 41020838, 2025). "The drug causes T-cells to become more active and leads to greater levels of interferon-gamma (IFN-γ) and tumor necrosis factor-alpha (TNF-a) in the tumor microenvironment." (PMID 40004731, 2025). "In contrast, poor prognosis involved TNF signalling and cytoskeleton-related pathways, indicating more aggressive tumour behaviour." (PMID 41007296, 2025). "M1-like macrophages typically exert anti-tumor effects by secreting proinflammatory factors such as IL-6/TNF-α in CRC and prostate cancer (PCA), IL-1α/IL-6 in lung cancer." (PMID 40380196, 2025). "An increase in TNFα induces apoptosis (programmed cell death) and necrosis (cell death due to injury), disrupts blood vessels, thus depriving tumor cells of blood supply." (PMID 41226575, 2025). "It has been evidenced that TNF‐α augments the invasion and metastasis of tumor cells by activating the NF‐κB signaling pathway and inducing EMT." (PMID 40226936, 2025). "TNF-α also performs significant functions in the early stages of cancer development, contributing to the tumor microenvironment and supporting the progression and survival of tumors." (PMID 40191430, 2025). "In cancer, ammonia is recycled and serves as a source of nitrogen to build amino acids, promote the growth of tumor biomass, support autophagy, and protect cells from TNFα-induced cell death." (PMID 40163355, 2025). "In animal models, TNF plays a critical role in tumor cell destruction through its activation of natural killer cells and CD8 lymphocytes." (PMID 40427207, 2025). "Several cytokines are known to be involved in tumor development and immune modulation, including tumor necrosis factor (TNF)-α, IL-6, IL-10, IL-12, IL-17, transforming growth factor (TGF)-β, and macrophage migration inhibitory factor (MIF)." (PMID 41051525, 2025). "Apart from its involvement in tumor invasion and metastasis, TNF-α plays a crucial role in the occurrence and progression of coronary heart disease." (PMID 40251177, 2025). "Consumption of germinated brown rice significantly reduced the IL-6 and TNF-α levels, thereby inhibiting inflammation and tumor development in the Gbrown group." (PMID 40869014, 2025). "By attenuating COX-2 expression, downregulating pro-inflammatory cytokines (TNF-α, IL-6), and interfering with phosphorylation-dependent transcriptional activation, pecan bioactives effectively reduce the tumor-promoting microenvironment." (PMID 41226270, 2025). "TNF signaling, primarily from macrophages to OS cells and CAFs, points to a central role for inflammation in tumor-stroma interaction and possibly in stromal activation and immune suppression." (PMID 40895569, 2025). "In cancer, TNF-α has an essential role, exhibiting both pro-tumor and anti-tumor effects depending on the context and stage of cancer development." (PMID 40933989, 2025).
tumor (continued). "Persistent expression of inflammatory factors produced within the tumor microenvironment, including GM-CSF, G-CSF, IL-6, IL-1β, TNF-α, and IFN-γ, is known to promote the expansion of immunosuppressive cells." (PMID 40822347, 2025). "Engineering bacteria to acutely produce cytokines, such as INF-γ, or increasing the bacterial presentation of PAMPs to increase the macrophage induction of TNFα reduces long-term tumor volume." (PMID 40722443, 2025). "Previous studies have associated these cells with anti-tumor effects, including increased secretion of effector molecules such as IFN-γ and TNF-α." (PMID 39858472, 2025). "The authors suggested that TAMs increase tumor cell glycolysis by secreting TNFα and elevate tumor hypoxia by enhancing AMP-activated protein kinase and PPARγ coactivator 1-α." (PMID 39865337, 2025). "One study has shown that platelet aggregation induced by tumor cells protects tumor cells from tumor necrosis factor-α mediated cytotoxicity, which helps tumor cells evade the body’s immune system." (PMID 39941717, 2025). "Key microglia-associated genes, including TREM2 and CX3CR1, regulate immune suppression, tumor proliferation, and invasion, while IL-1β and TNF-α contribute to tumor-promoting inflammation." (PMID 40076502, 2025). "The inflammatory microenvironment formed by inflammatory factors such as IL-1β, TNF-α, and IL-6 can promote the proliferation and interstitial transformation of tumor cells, thereby inducing their invasion and metastasis to adjacent or distant tissues." (PMID 40606986, 2025). "For example, TLR-4 activation leads to an increase in substances like interleukin-6 (IL-6) and tumor necrosis factor-alpha (TNF-alpha), which can help tumor growth." (PMID 40727443, 2025). "M1-type macrophages in the tumor microenvironment can activate immune cells by secreting pro-inflammatory factors (TNF-a, IL-1, IL-6), enhancing anti-tumor immunity." (PMID 40557160, 2025). "Tumor sections from mice subjected to Ce6@Lip-TD and Ce6/CpG@Lip-TD with laser treatments exhibited markedly elevated levels of tumor necrosis factor α (TNF-α, red fluorescence) and interleukin 6 (IL-6, green fluorescence) compared to other groups." (PMID 40177379, 2025). "In myeloid cells, the target genes regulated by malignant cells were enriched in IL−17 signaling pathway and TNF signaling pathway, highlighting their involvement in immune regulation and inflammation within the tumor microenvironment." (PMID 40145096, 2025). "Tumor co-culture induced further enhancement of M1-associated markers including CD80/CD86, MHC-II and IL-1β/IL-6/TNF-α/IL-12/IFN-γ, while suppressing M2 markers CD163/CD206, indicating tumor-triggered M1 polarization." (PMID 41388305, 2025). "These cytokines play critical roles in immune activation and tumor cell destruction; IFN-γ enhances the cytotoxic activity of T cells and natural killer (NK) cells, while TNF-α promotes inflammation and apoptosis of tumor cells." (PMID 39930509, 2025). "On the contrary, various chemical mediators released by TAMCs, such as TNF-α, IL-1, IL-6, tryptase, chondroitin, and sulfate, trigger antitumor immune responses, including inflammation leading to apoptosis in the tumor." (PMID 40805183, 2025). "Tumor cells secrete growth factors that disrupt bone homeostasis, including tumor necrosis factor (TNF), which is elevated in cancer patients." (PMID 41374347, 2025). "Secondly, once activated, NKCs directly eliminate target cells and modulate the immune response by secreting perforin, granzymes, and cytokines such as IFN-γ and TNF-α, thereby performing anti-tumor and antiviral functions." (PMID 40766304, 2025). "Pro-inflammatory cytokines such as interleukin (IL)-6, IL-1β, IL-8, and tumor necrosis factor-alpha (TNF-α) are frequently upregulated and contribute to tumor cell proliferation, migration, and invasion." (PMID 40612845, 2025).